KRAS (KRas proto-oncogene, GTPase)
Diseases named in the same sentence as KRAS in open-access papers (continued):
Sharing a sentence is not in itself a finding about the gene and the disease.
tumor (continued). "Previous mutation analysis of tumor tissue samples reported significant associations between certain clinical features among Vietnamese NSCLC patients and the prevalence of EGFR and KRAS mutations." (PMID 32850431, 2020). "The prevalence of KRAS and BRAF mutations was found to vary significantly by tumor location, with mutations more prevalent among right‐sided metastatic colon cancers than left‐sided tumors." (PMID 31856410, 2020). "We have identified a tipping point between regeneration versus neoplastic progression and propose a mechanism by which KRAS swings the balance towards neoplasia by blocking ciliogenesis, such that cells are unable to respond to Hh and regenerate." (PMID 32571902, 2020). "The standard techniques evaluating KRAS mutation status for the decision about anti-EGFR mAb therapy are based on formalin-fixed, paraffin-embedded (FFPE) specimens of tumor tissue obtained during surgery (tissue biopsy)." (PMID 32867151, 2020). "Although these studies provide evidence directed toward a pro-tumourigenic function of STAT3 signalling in KRAS-induced cancer, it has also been shown to act as a tumour-suppressor in LAC24." (PMID 33116132, 2020). "Early studies showed that Bup exhibited preferential inhibition of tumor cells bearing PIK3CA mutations, in contrast to either KRAS or PTEN mutant models." (PMID 32825725, 2020). "The analyses from tumor DNA detected both meth-HOXA9 and mut-KRAS in each tumor, but the levels varied." (PMID 33322500, 2020). "Heterogeneity was observed in 14 of 27 (51.9%) amplified tumors taking together heterogeneity within the primary tumor and those 3 cases with only KRAS amplified metastasis." (PMID 32571252, 2020). "miR-487b and miR-203 have been noted to work as tumor suppressive miRNAs in lung cancer by targeting KRAS, WNT5A, SUZ12, MYC, and BMI1 (miR-487b) and FZD2 (miR-203)." (PMID 32316322, 2020). "In KRAS-mutant tumours existing treatment options, e.g. MEK inhibition, have limited efficacy due to resistance through feedback activation of epidermal growth factor receptors (HER)." (PMID 32147669, 2020). "The decision model describes the influence of pT stage, number of lymph nodes evaluated, tumor sidedness, MSS status, BRAF mutation status, and KRAS mutation status on relevant outcomes, such as the recurrence rate and disease-specific survival." (PMID 32458162, 2020). "A miR181ab1 signature predicting poor prognosis in KRAS-driven cancers includes genes with a tumor-suppressive role." (PMID 31874105, 2020). "Comparatively fewer studies have focused on miRNAs with a pro-oncogenic role in the context of mutant-KRAS tumorigenesis, in contrast with the wealth of information about tumor-suppressive miRNAs reported to downregulate KRAS expression." (PMID 31874105, 2020). "Upon intratumoral injection, siG12D is released locally, thereby preventing translation of KRAS proteins and potentially inhibiting growth of tumor cells that normally overexpress KRAS." (PMID 33113880, 2020). "In a prospective study of 106 patient samples of CRC, ctDNA analysis of KRAS and BRAF mutational status was compared to the analysis of tumor tissue." (PMID 32010431, 2020). "ABT-263 relieves the inhibition of BCL-XL to BIM; hence, the MEK inhibitor-induced expression of the pro-apoptotic protein BIM increases cell apoptosis and reduces the tumour volume in KRAS mutant cancer models." (PMID 33008426, 2020). "In this study we investigated associations between serum lipid profile, BMI and metabolic factors with KRAS status according to primary tumour location." (PMID 32594310, 2020). "Activated KRAS mutation-specific T cells can kill KRAS-mutant tumor cells, leading to the inhibition of KRAS-mutant tumor growth." (PMID 32903495, 2020). "The expression of circ-MEMO1, miR-101-3p, and KRAS in tumor tissues was detected by Western blot assay and qRT-PCR." (PMID 33005174, 2020).
tumor (continued). "From this observation, we conclude that the depletion of KRAS mutant tumor cell clones can support the growth of wild-type clones." (PMID 32766143, 2020). "Consistent with the GSEA data, KRAS was preferentially expressed in the edge tumor cells and both c-Myc and CHEK1 were present in the core regions, To further validate these results, we developed another model by using slice cultures of neonatal mouse brains." (PMID 32938908, 2020). "Calmodulin-dependent GTPase signalling is coupled to pathological settings, as KRas and Rac1 are often drivers of signalling pathways that critically stimulate tumour formation and progression." (PMID 32456244, 2020). "Further, KRAS gene is frequently mutated in human cancers, and CRC harboring KRAS mutation induces continued oncogenic KRAS expression for tumor maintenance." (PMID 31947604, 2020). "To date, it has been shown that KRAS and BRAF mutations increase the glycolytic capacity of tumor cells and their glutaminolysis." (PMID 32231083, 2020). "Flow cytometric analysis showed that the percentage of apoptosis in these KRAS-dependent tumor cell lines was significantly higher than that of controls." (PMID 33122197, 2020). "Altogether, both primary tumor and a metastasis were genotyped in 15 cases and the KRAS status was concordant in 13/15 (87%) cases." (PMID 33226505, 2020). "Zdanov and colleagues showed that KRAS-mutant tumour cells induced the conversion of CD4+ cells to Tregs." (PMID 33116132, 2020). "Among cases with respective tumor marker data, 19.8% were MSI-H (n = 719), 24.3% were CIMP-positive (n = 841), 18.4% were BRAF-mutated (n = 654), and 32.0% were KRAS-mutated (n = 1098)." (PMID 32923935, 2020). "Promisingly, AMG-510, the first inhibitor of KRAS in clinical development, caused a decline in KRASG12C tumor growth and augmented the efficacy of chemotherapy and targeted agents." (PMID 33256814, 2020). "Here the authors demonstrate the specific targeting of endogenous KRAS protein for degradation from cancer cells, and regression of tumours expressing mutant KRAS in a mouse model." (PMID 32591521, 2020). "In a retrospective analysis of tumor patients, OS after cetuximab treatment was higher in patients with KRAS wild-type tumors (9.5 vs. 4.8 months)." (PMID 32793499, 2020). "As the oncogene KRAS has been found upregulated in many human malignancies, the regulation of KRAS by miRNAs has drawn attention in the field, since specific miRNAs can act as tumor suppressor by targeting KRAS also in CRC." (PMID 32676506, 2020). "Driver mutations most frequently acquired at relapse were those in KRAS and NRAS, detected in three and two tumours respectively." (PMID 33057009, 2020). "KRASP1 affects tumor growth and development by competitive binding for shared miRNAs with KRAS proto-oncogene, GTPase (KRAS)." (PMID 32906679, 2020). "On the other way, upregulation of miR-21 in NSCLC enhances KRAS-driven tumor initiation via repressing tumor suppressors including programmed cell death 4 (PDCD4) and apoptosis peptidase activating factor 1 (APAF1)." (PMID 32316322, 2020). "In our study, the positive BRAF, KRAS and NRAS mutations in the bone marrow tumor DNA samples were 28/83 (34%), but it was 9/17 (53%) in the plasma cfDNA samples, which demonstrated a significantly higher detection rate." (PMID 32284750, 2020). "When KRAS is mutated, the downstream signaling pathway (mitogen-activated protein kinase, MAPK) is activated, leading to cellular proliferation and tumor progression." (PMID 33254149, 2020). "Various pathways of progression have been reported for IPMN-related invasive PC, some of which involve mutations in KRAS, GNAS or other tumor suppressor genes." (PMID 32937962, 2020).
tumor (continued). "Some of the tumor tissues reported in this study had been already characterized for driving lesions such as BRAFV600E and H/N/KRAS mutations, as well as RET and TRK gene fusions." (PMID 31906302, 2020). "This system enables more detailed study of the biological interactions between KRAS mutant cancer cells and the tumor microvasculature." (PMID 33013881, 2020). "In a study comparing KRAS and BRAF mutations in both metastatic CRC plasma cfDNA and tumour tissue, specificity and sensitivity of 100% for BRAF V600E mutation and 96% on KRAS point mutations have been demonstrated." (PMID 33144898, 2020). "The analyzed large scale of the primary tumor revealed a heterogenous distribution of KRAS amplified tumor cells in this case." (PMID 32571252, 2020). "As a result, few prognostic factors have been identified in SIACs such as tumor location (duodenum vs. jejunum and ileum), microsatellite instability (MSI), tumor-infiltrating lymphocytes (TILs), and KRAS or BRAF mutations." (PMID 32781596, 2020). "For example, both tumor samples and PDOs harbored driver mutations in four patients (EGFR L858R, n = 2; EGFR Ex20 ins, n = 1; and KRAS G12C, n = 1)." (PMID 32633046, 2020). "Simultaneous therapies that reverse the T cell suppressive tumor microenvironment in KRAS/STK11 NSCLC would be required for a potent response." (PMID 32560574, 2020). "In order to exert these effects, oncogenic KRAS expressed in tumour cells remodels the surrounding stroma cells by inducing several molecules such as cytokines, chemokines and growth factors." (PMID 33116132, 2020). "It turns out that two variant-associated genes KRAS and APC exist in five out of seven primary tumor samples and six out of seven primary tumor samples, respectively." (PMID 32901013, 2020). "A recent deep-sequencing study on a small cohort of four KRAS mutant patients found complete concordance between the primary tumor and its metastases." (PMID 32725342, 2020). "Its ability to bind to high-affinity EGFR ligands (e.g., HB-EGF, TGFα, BTC, and EGF) contributes to its anti-tumor efficacy against KRAS-mutant colorectal cancer (CRC) in a patient-derived xenograft (PDX) model resistant to cetuximab treatment." (PMID 33142709, 2020). "MTT results showed that higher concentration state of H-REV107 peptide had an effect on the proliferation of wild-type KRAS A549 cell line than other tumor cell lines." (PMID 32486141, 2020). "From our previously established H358 and H1299 stable cell lines, we isolated unique clones of pan-RAS/KRAS degraders that would additionally express a Firefly Luciferase (FLuc) to detect the tumour in vivo." (PMID 32591521, 2020). "Following intraperitoneal injection, exosomes loaded with siRNA accumulated to a greater extent in the pancreas, and were also more growth inhibitory in a KRAS mutant orthotopic tumor xenografts model compared with liposomes carrying the same siRNA." (PMID 32117755, 2020). "In a second phase II trial, patients with KRAS-mutated and chemotherapy-refractory CRC were treated with temsirolimus until tumor progression, and with a combination of temsirolimus and irinotecan from this point onwards (NCT00827684)." (PMID 32455578, 2020).
tumor (continued). "As a driver mutation, the KRAS mutant is conceptually attractive since it is tumor-specific and biologically important to tumor progression and is likely to be expressed in all kinds of tumors, which makes the KRAS mutant a hot spot for adoptive cell therapy." (PMID 32194541, 2020). "A large analysis, testing 1343 NSCLC tumor samples with NGS, showed a significant association between EGFR and PI3KCA or CTNNB1 mutations and between KRAS and STK11 mutations." (PMID 32365882, 2020). "The genotyping studies establish a concordance of more than 90% between KRAS tests in tumor tissue and ctDNA, making it possible to test in ctDNA LB as valid for tissue tests in patients with colorectal cancer." (PMID 32629823, 2020). "This process of cellular recycling protects tumor cells from cytotoxic effects of KRAS pathway blockage." (PMID 32560574, 2020). "In summary, the molecular analysis of a small amount of unamplified cfDNA for BRAF, KRAS and NRAS mutations in MM patients is feasible and has good concordance with standard mutations testing of bone marrow tumor DNA samples." (PMID 32284750, 2020). "In patients with double (KRAS and BRAF) wild-type tumor, median OS was 10 months if CDX2 loss (n = 10) compared to 27 months if CDX2 expressed (n = 77) (p = 0.576)." (PMID 32117703, 2020). "For further detail analysis, the agreement of cfDNA and tumor DNA of BRAF V600Mx was 76%, KRAS Mx and NRAS Q61 mutations were 100%, NRAS G12/G13 mutations was 100%." (PMID 32284750, 2020). "In human colorectal cancer (CRC) and non-small cell lung cancer (NSCLC) tissue, CD73 staining is increased in KRAS mutant compared to wild-type tumor." (PMID 32351498, 2020). "The EGFR-targeting antibody cetuximab is also used under the prerequisite of wildtype KRAS or BRAF status, as mutations in these oncogenes render tumours insensitive to EGFR-targeted therapy." (PMID 32647253, 2020). "In EGFR mutant tumors, wild type to KRAS mutant conversion of the tumor was frequent (30%), while in KRAS mutant tumors, the wild type KRAS subclonality was frequent (30%)." (PMID 32725342, 2020). "Potential examples of such tumor-agnostic targets other than NTRK include (but not limited to) ALK, BRAF, BRCAness, FGFR, HER2, HER3, homologous recombination deficiency (HRD), KRAS, RET, ROS1, tumor mutation burden (TMB) high." (PMID 31974683, 2020). "A western blot (WB) assay revealed markedly reduced expression levels of KRAS and KRAS G12S mutant proteins in the tumor tissues of A549 cells-engrafted mice edited by AdV-Cas9-sgG12S, but not in the AdV-Cas9 treated control group." (PMID 32308773, 2020). "For our dataset, the best clusters were formed using three input features–histological grade, tumor site, and city–with genetic KRAS characteristics blindly color labeled to reveal interesting patterns and separation." (PMID 32628708, 2020). "Some authors found that up to 50–65% of patients with wild-type KRAS tumours were resistant to EGFR monoclonal antibodies." (PMID 33183271, 2020). "Interesting possibilities to explore would include KRAS- or ERK-driven tumours with high NHE1 expression." (PMID 32242030, 2020). "Apart from the pro-inflammatory function of KRAS, the oncogene often co-operates with other oncogenes or tumour-suppressor genes in the process of immune evasion in cancers." (PMID 33116132, 2020). "Activating MAPK pathway mutations including KRAS c.35G>A (p.G12D; COSM521) and GNAS c.601C>T (p.R201C; COSM27887) were identified in two tumor samples (2/15, 13%), with these mutations co-occurring in both tumors (NECC015, NECC012)." (PMID 32544169, 2020).
tumor (continued). "Oncogenic KRAS plays a key role in promoting macropinocytosis with the help of αvβ3 and galectin-3 on the surface of tumor cells." (PMID 32122374, 2020). "The KRAS fraction abundance positively correlated between primary tumor tissue and liver metastases samples (R = 0.8, p < 0.001, n = 61)." (PMID 32867151, 2020). "Other prognostic factors that are known to influence response after treatment with radioembolization are (among others) KRAS status, primary tumor location, percentage tumor involvement, and pre-treatment CEA level." (PMID 32960390, 2020). "Perverting the course of their intended function, KRAS-mutated cancers use endogenous TNF-related apoptosis-inducing ligand (TRAIL) and its receptor(s) to promote tumor growth and metastases." (PMID 32194994, 2020). "Vaccination against KRAS-G12D with the SLP–Lpx before implantation of the MC38-G12D tumors markedly inhibited tumor growth." (PMID 33298945, 2020). "Activating mutations of KRAS codon 12 were detected in four patients, and oncogenic mutations of NRAS (G13V) and BRAF (V600E) were each identified in one additional tumor, contributing to a prevalence of 54.4% for activating mutations of RAS pathway." (PMID 31953485, 2020). "From the previous studies, miR-143 functioned as tumor suppressor miRNA in several malignancies through targeting KRAS and its effector molecules." (PMID 32370060, 2020). "Even in the few KRAS wild-type tumours, somatic mutations activating the RAS-MAPK pathway up- or downstream of KRAS have been identified." (PMID 32727085, 2020). "It is well known that the presence of KRAS and BRAF mutations in a patient’s tumor correlates strongly with resistance to anti-EGFR antibodies, and therefore, all patients are tested for BRAF and KRAS mutations before initiating anti-EGFR therapy." (PMID 32290033, 2020). "KRAS, a member of the small GTPase superfamily, is mutated in over 90% of human pancreatic ductal adenocarcinomas (PDAC) and is associated with tumor cell proliferation and reduced patient survival." (PMID 33113880, 2020). "microRNA-143 (miR-143) is a well-known tumor suppressive microRNA that exhibits anti-tumoral function by targeting KRAS signaling pathways in various malignancies." (PMID 32370060, 2020). "The co-occurrence of KEAP1 and KRAS mutations suggests that KEAP1 mutations either affect NRF2 activity differently than KRAS-stimulated overexpression of NRF2, or are affecting other signalling pathways that are beneficial to the tumour." (PMID 33276631, 2020). "The subpopulation of dormant tumor cells with mutant KRAS oncogene has features of cancer stem cells and relies on mitochondrial respiration and OXPHOS, demonstrating decreased dependence on glycolysis as a source of energy." (PMID 32252351, 2020). "On the other hand, vitamin C reversed STS-induced ferritin downregulation in KRAS-wild-type tumor cells." (PMID 32393788, 2020). "Multiple ERBB RTKs and several of their ligands are expressed and active from the earliest stage of KRAS-driven tumor development in men and mice." (PMID 32560574, 2020).